THBS2 (thrombospondin 2)
Diseases named in the same sentence as THBS2 in open-access papers (continued):
Sharing a sentence is not in itself a finding about the gene and the disease.
cancer (continued). "The Cancer Genome Atlas (TCGA) dataset and Gene Expression Omnibus (GEO) (GDS4382, GSE6988, GSE35834) were used to analyzed the mRNA expression of THBS2." (PMID 33244454, 2020). "THBS2 is a member of the THBS family, which is reported to be regulated by the microRNA network in human cancer." (PMID 33244454, 2020). "From various cancer formation and metastasis signals, it can be seen that a set of matrix metalloproteases (MMPs) (MMP27, MMP23B, THBS2, MMP13, MMP11) as well as the MMPs receptor ITGB3 were inhibited in GX0101-infected CEFs." (PMID 27200301, 2016). "The functions of two genes (P4HA2 and THBS2) in our signature of OSCC recurrence and their roles in cancer are not well understood." (PMID 21989116, 2011). "Some of these potential proteins (COL12A1, THBS2, S100A8, and S100A9) were reported to associate with other cancers and non-malignant diseases, which limited the clinical validity of the potential proteins in CRC." (PMID 38302471, 2024). "Both THBS1 and THBS2 share the TSR2 domain that interacts with the epidermal growth factor receptor (EGFR), which in turn is known to activate the PI3K/Akt/mTOR downstream signal pathway, known to be involved in cancer cell growth and survival." (PMID 38339060, 2024). "Among these, THBS2 and COMP were upregulated in cancer tissue." (PMID 38827236, 2024). "We also explored the predictive efficacy of the four proteins (COL12A1, THBS2, S100A8, and S100A9) in multi-cancer cohort composed of 115 plasma samples from 95 patients with treatment-naive patients with various cancer types and 20 HCs, and two public cohorts related to the non-malignant diseases." (PMID 38302471, 2024). "However, further investigation is warranted to validate the therapeutic potential of THBS2 and GPR132 in cancer." (PMID 37884956, 2023). "Furthermore, the correlation of THBS2 expression with CIN, LOH, MSI and TMB was assessed in pan-cancer." (PMID 37884956, 2023). "Indeed, transfecting TF in cancer cell lines induced increased transcription of VEGF and reduced transcription of thrombospondin 1 (TSP1) and thrombospondin 2 (TSP2) secreted by platelets, indicating the proangiogenic role of TF." (PMID 37719444, 2023). "Genes positively correlated with purity showed enrichment in cancer-related pathways and processes such as epithelial-mesenchymal transition (BASP1, COL4A1, THBS2), genes involved in the TNFA signaling via NFKB (SPSB1, SMAD3), and genes upregulated by KRAS activation (CFB, MAFB)." (PMID 37041233, 2023). "Among these, we found interactions that may constitute potential targets for CAFs-based therapies, such as THBS2/THBS3 (myCAF2) and CD47 (cancer cells) or between MDK (CAFs) and SDC2/SDC4/NCL (cancer cells)." (PMID 36352420, 2022). "myCAFs may also express other matrix proteins including THBS1 (thrombospondin 1), THBS2, and TNC (tenascin C, a matrix protein), to communicate with immunocytes, smooth muscle cells, cancer cells, and plasma cells through CD44, integrin (α3β1), and SDC1." (PMID 35986392, 2022). "In both of these examples, these gene lists are clearly due to the presence of the COL11A1/INHBA/THBS2-expressing CAFs and therefore these are not cancer-type specific subtype signatures." (PMID 34283835, 2021). "Meanwhile, significant coexpression relationships between THBS2 and Tfh cell’s surface marker coding genes had been observed in tissue levels, but not in cancer cell lines." (PMID 31608101, 2019). "CYP24, FOSB, PCDH10, THBS2, and RASSF5 were selected as representative genes for further analysis, as they are well-known regulators of cancer cell proliferation and apoptosis, and the results obtained by qPCR analysis were shown to support our previously obtained results." (PMID 29156803, 2017).
cancer (continued). "We found a significant difference in the mean of expression levels for thrombospondin-2 between recurrent and non-recurrent cancer cases, with the lowest levels in the recurrent cases." (PMID 12189553, 2002). "Notably, the correlation between THBS2 expression and EMT activity varied in cancers." (PMID 39732719, 2024). "Furthermore, inhibiting THBS2 expression significantly suppresses EMT and cancer cell metastasis." (PMID 38827236, 2024). "THBS2 expression was significantly correlated with the infiltration levels of B cells in 10 cancer types, dendritic cells in 6 cancer types, macrophages in 12 cancer types, neutrophils in 4 cancer types, CD4 + T cells in 17 cancer types, and CD8 + T cells in 8 cancer types." (PMID 35701829, 2022). "Besides, other studies have identified genes with significantly different methylation between different subtypes, and the differentially methylated genes (including CDKN2A, APC, CDH13, THBS2 and ERG) have been utilized to distinguish these different histological subtypes of cancers." (PMID 26862903, 2016). "Overall, we validated the consistency of up-regulation of the four proteins (COL12A1, THBS2, S100A8, and S100A9) was only observed in CRC but not in other cancer types; and the four proteins could achieve good performance in the diagnosis of CRC, but not other cancer types." (PMID 38302471, 2024).
infection (15 papers, 2011 to 2025). The state of being infected such as from the introduction of a foreign agent such as serum, vaccine, antigenic substance or organism. "BMSCs and THBS2-deficient BMSCs were treated with or without the supernatant of H. pylori for 12 h at a multiplicity of infection of 50, and their EVs were collected." (PMID 37798762, 2023). "Finally, there was a nonsignificant increase in thrombospondin-2 levels 48 h after infection with LASV, but not MOPV." (PMID 35337059, 2022).
cardiovascular diseases (7 papers, 2018 to 2025). "THBS2 modifies JAG1–NOTCH2 interactions in vitro and a THBS2 SNP is associated with cardiovascular diseases." (PMID 37600608, 2023). "Both thrombospondin-1 and thrombospondin-2, however, have been studied in cardiovascular disease and mediate atherosclerotic plaque development in mice." (PMID 37944753, 2023). "Thrombospondin-2 (TSP2) is a matricellular protein that interacts with various ligands such as extracellular matrix (ECM) structural proteins and is implicated in the pathogenesis of cardiovascular diseases (CVD)." (PMID 36335340, 2022). "It belongs to the Thrombospondin family, which is known to play an important role in cardiovascular diseases, although THBS1 is the best-known member and THBS2 itself has not been deeply studied." (PMID 32605321, 2020).
heart disease (3 papers, 2019 to 2022). "However, Thbs3 is unique in that it functions opposite to Thbs1, Thbs2, and Thbs4, where it enhances cardiac pathology with disease stimulation, while mice deficient in Thbs3−/− were partially protected from cardiac disease." (PMID 30622267, 2019).
digestive diseases (2 papers, 2023 to 2025). "Notably, leptin (LEP), GDF15, and ADM showed the strongest associations with lung function, while BST2, THBS2, and CEACAM1 exhibited the most significant associations with digestive diseases." (PMID 40048323, 2025).
vascular disorder (1 paper, 2020). A general term used to describe any disease affecting blood vessels]. "Five proteins, THBS2, LASP1, LAMB3, ITGAV, and COL11A1A, were selected according to their GO classification, the Kyoto Encyclopedia of Genes and Genomes (KEGG) pathways in which they can be involved and their relationship with AAA or vascular disorders." (PMID 32605321, 2020).
THBS2 also shares sentences with these, for which no sentence is quoted: schistosomiasis (22 papers); atherosclerosis (5); cardiac hypertrophy (4); myocardial infarction (4); oral cancer (4); bladder cancer (3); Brachycephaly (3); clear cell renal cell carcinoma (3); epilepsy (3); glaucoma (3); glomerulonephritis (3); intrahepatic cholangiocarcinoma (3); metastatic colorectal cancer (3); osteosarcoma (3); chronic allograft nephropathy (2); chronic kidney disease (2); colorectal adenoma (2); dilated cardiomyopathy (2); glomerulosclerosis (2); Hepatitis (2); ischemia (2); lymphoma (2); opisthorchiasis (2); osteoarthritis (2); parasite infection (2); proliferative retinopathy (2); ulcerative colitis (2); acute kidney injury (1); adenocarcinoma (1); Alagille syndrome (1).
A further 75 diseases each share a sentence with THBS2 in 1 paper.